IL1B (interleukin 1 beta)
Diseases named in the same sentence as IL1B in open-access papers (continued):
Sharing a sentence is not in itself a finding about the gene and the disease.
tumor (continued). "The proinflammatory cytokines, IFN-γ, IL-4, IL-6 and IL-1β, promote MDSC expansion and activation and generate reactive oxygen species (ROS) and nitric oxide (NO), which contribute to immunosuppression and reduced T cell function within the tumor microenvironment." (PMID 35655772, 2022). "The results obtained in vivo showed that through local reduction of oxidative stress and inflammation (IL-1β, TNF-α), the Emorsan® Gel significantly reduced the infiltration of mast cells into the injured wound, leading to the amelioration of symptoms such as itch and skin irritation." (PMID 35563099, 2022). "Finally, we showed that the KRAS blocker deltarasin acts to downregulate IL1R1 (interleukin-1 receptor 1) expression in KRAS-mutant tumor cells and that the proposed KRAS/CCL2/IL1B signature is enriched in human cancers with high KRAS mutation frequencies, in which it portends a dismal prognosis." (PMID 35327394, 2022). "Notably, the vast majority of these relationships were negative associations with the bacteria, spleen cytokines, spleen FISH staining, brain Il-1β, and serum LBP that were all higher in Tumor mice (given that the relative abundance of Lactobacillus was lower in Tumor and Resected mice)." (PMID 35248004, 2022). "However, recent reports demonstrate that the immunomodulatory functions of succinate are more complex, as it can suppress the secretion of the inflammatory mediators IL-6, tumours TNF-α and NO, as well as inhibit IL-1b mRNA transcription in inflammatory macrophages." (PMID 35216253, 2022). "For instance, BGL was found to inhibit the release of IL-1β upon NLRP3 inflammasome activation, and BGL can also promote the maturation of tumor-educated dendritic cells (TEDCs), which subsequently enhances antitumor immune responses and inhibits tumor progression." (PMID 36142202, 2022). "We, therefore, investigated whether targeting other members of the IL-1 pathway (Caspase-1, IL1β or IRAK1) could reduce bone metastases without increasing tumour growth outside of the bone." (PMID 36230739, 2022). "Intriguingly, decreased gene expression of both pro- (Il-1β and Il-6) and anti-inflammatory (Il-10 and Tgf-β) players, as well as T CD8+ dependent effector function genes such as granzyme (Gzma) and perforin (Prf1) in TME of Opn4KO was found when compared to Opn4WT tumor-bearing mice." (PMID 35562405, 2022). "Indeed, both yeast extract and WGP attenuated tumor growth at the 4th week of the experiments, with the reduction in serum IL-1β and IL-6, but not TNF-α and IL-10, supporting a previous publication." (PMID 36142859, 2022). "Accumulating data indicate that IL-1β activates 2 major downstream effectors, the NF-κB and MAPK pathways, to stimulate the expression of adhesion molecules such as ICAM1 and VCAM1 in diverse cell types including tumor cells, thereby amplifying and sustaining responses to IL-1β." (PMID 36264639, 2022). "Furthermore, IL-1β and other factors, which were also strongly elevated in CIS, are important factors for inflammasome activation, a process for which both tumor-promoting and -inhibiting effects have been described." (PMID 35563820, 2022). "This may suggest that activated caspase-1 is associated with the initiation of inflammatory programmed cell death (pyroptosis) and, in turn, inhibits tumor growth rather than upregulating pro-inflammatory molecules such as IL-1β and IL-18." (PMID 35883451, 2022). "Additionally, tumor hypoxia with resulting acidosis is known to abrogate the function of surrounding immune cells via the induction of anti-immunogenic mediators (e.g., IL-1b, IL-8, IL-6, TNFα, and TGF-b) contributing to tumor cell escape of immunogenic control." (PMID 34831136, 2021). "Moreover, IL-1β induces lipolysis of adjacent adipocytes and the expression of metastasis-related and inflammatory factors such as matrix metalloproteinases (MMP), COX-2, CCL2, IL-6, TGF-β, and IL-8 which promote tumor growth and bone metastasis." (PMID 34064859, 2021).
tumor (continued). "However, it is also attractive to speculate that increased inflammasome-dependent IL-1β secretion stimulates potent cytotoxic T cell responses by CD8+ T cells, as was very recently reported in the context of anti-tumor immunity." (PMID 33578743, 2021). "Moreover, combination treatment showed downregulation of the expression of inflammation-related genes that are involved in tumor inflammation, such as Gremlin (GREM1), IL-1β, IL-4, NF-κB, and prostaglandin-endoperoxide synthase 2 (PTGS2), tumor nitric oxide level." (PMID 34959865, 2021). "Similarly, nuclear protein expression of Gli1 and NF-κB p65 was significantly enhanced in tumor tissues from SW1990 cells treated with IL-1β, TNF-α and Shh, whereas no significant expression was observed in the tissues from BxPC-3 cells." (PMID 34046348, 2021). "At the same time, there was a large overlap between the genomes of PMN-MDSCs and M-MDSCs involved in immunosuppression, such as IL-1B, ARG-2, CD84, and WFDC17, and chemokine receptors, such as CCR2 and CXCR2, revealing that MDSCs could be migrated to the primary tumor by tumor-derived chemokines." (PMID 34527668, 2021). "Inflamed VAT is a major contributor to the progression of systemic inflammation by secreting numerous pro-inflammatory cytokines including IL-1β, IL-6, and TNF-α into systemic circulation, which could have a remote effect leading to an increase in tumor aggressiveness." (PMID 35010352, 2021). "Finally, we confirm the importance of MyD88 in macrophages showing that BCG induces the release of inflammatory cytokines (TNF-α, IL-6, IL-1β) and nitric oxide by WT macrophages in co-culture with infected tumor cells, but not in MyD88−/− BMDMs." (PMID 34341449, 2021). "However, the pathophysiological role of IL-18 in tumor microenvironment has not been well-defined compared to that of IL-1β." (PMID 33686176, 2021). "Interestingly, we observed that although the serum levels of several cytokines including IL‐6, TNF‐α, and IL‐1β (but not IL‐1α) increased in C26‐tumor‐bearing mice, these effects were prevented by treatment with GW (Fig EV3, EV4D–G)." (PMID 34096686, 2021). "After addressing the role of stromal-derived IL-1B signalling by using parental E0771 in mice lacking IL-1B or IL1R1, next we investigated whether tumour-derived IL-1B rescues the lack of microenvironment-derived IL-1B." (PMID 34290237, 2021). "Mechanistically, this process is regulated by the IL-1β-producing myeloid cells, which subsequently activate endothelial cells to produce proangiogenic factors like VEGF, modulating the inflammatory brain microenvironment of the tumor and inducing an enhanced angiogenesis and tumor progression." (PMID 33466236, 2021). "Because of the involvement of cancer inflammation in promoting tumor aggressiveness, we determined the impact of glycolysis and OXPHOS on the activation of p65, which is a canonical transcription factor mediating the proinflammatory activities of TNFα and IL-1β." (PMID 34072893, 2021). "In our model, IL-1B drives the recruitment of innate immune cells that may elicit an anti-tumour response, irrespective of the source." (PMID 34290237, 2021). "Thus, IL-1β restrained FGF19/FGFR4-induced MAPK phosphorylation and tumor generation." (PMID 33981224, 2021). "The M1 macrophages produce pro-inflammatory factors (TNF-α, IL-1β, and iNOS), chemokines (CXCL10, CXCL11, and CCL2), antigen-presenting molecules such as MHCII, costimulatory molecules (CD86 and CD80), and antigen-treated peptidases, which play an anti-tumor role in cancer." (PMID 34034714, 2021). "Our results suggest that doxycycline has an inhibiting effect on LPS priming of the inflammasome, and that it can attenuate the production of pro-CASP1 and NLRP3 RNA and NLRP3 protein assembly irrespective of the level of IL-1β production and secretion in these tumor cells." (PMID 34577552, 2021).
tumor (continued). "The activated MSCs robustly support tumor progression and metastasis directly by inducing EMT, and indirectly through the production of numerous immunomodulatory molecules, such as TGFβ, PGE2, IL6, IL8, VEGF, TNFα, IL1β, IDO, and FSTL1, to generate and expand Tregs, MDSCs, and DCregs." (PMID 33535613, 2021). "Such a process might be altered by the addition of an IL1β-blocking agent, rendering tumor cells without the protection conferred by fibroblast-soluble factors, and avoiding NCF-to-CAF conversion." (PMID 34066976, 2021). "The tumour cell is not the only source of IL-1B; cells in the microenvironment, including immune cells, endothelial cells, osteoblasts and bone marrow cells produce IL-1B." (PMID 34290237, 2021). "The complex crosstalk within tumor microenvironment cellular players is mediated by several tumor-derived cytokines (e.g., vascular endothelial growth factor, VEGF; interleukin 1 beta, IL-1β; granulocyte/macrophage colony-stimulating factor, GM-CSF), which also have a role in immunomodulation." (PMID 34960055, 2021). "When released into tumor microenvironment, ATP acts on P2X7 purinergic receptors and triggers the NOD-like receptor family, pyrin domain containing-3 protein (NLRP3), allowing for the secretion of interleukin-1beta (IL-1β) then primes IFNγ-producing tumor antigen-specific CD8+ T cell in mice." (PMID 34094967, 2021). "Among them, we mainly analyzed four genes (EGFR and BMP1 in ESCC and IL-1B and MAPT in EAC) that were related to gender, tumor stage, lymph node metastasis, distant metastasis, and other clinical features in EC, supposing that they might play essential roles in the prognosis of EC patients." (PMID 33859939, 2021). "With reduced IL‐1β activity, there is less tumor-derived IL-1β and IL-6 activity on bone marrow cells and ultimately decreased STAT3 activity in this cell population, supporting our previous findings that tumor-NLRP3 activity induces IL-1β and IL-6 in the bone marrow." (PMID 34531850, 2021). "IL-1 is an immunosuppressive cytokine with two different isoforms, IL-1α and IL-1β, which is mainly produced by tumor cells and immune regulatory cells through autocrine or paracrine in the TME and plays an important role in promoting tumor occurrence and development." (PMID 34625124, 2021). "In agreement, a study in which the authors analyzed the expression of 50 cytokines (including IL-1β, IL-1 α, and IL-1RA) in the saliva of 16 OSCC patients before and after surgical intervention, showed a significant decrease in salivary IL-1β levels after tumor resection." (PMID 35048046, 2021). "However, the impacts of consistent proinflammatory stimulation by TNFα + IL-1β—reflecting chronic inflammatory processes that take place at the tumor site—were not investigated in TNBC." (PMID 34072893, 2021). "Given the increase in production of IL‐1β, TNF‐α, IL‐12, IL‐22, and IL‐6 by the expanded inflammatory Ly6C+MHCII+ monocyte population in the tumor following the administration of SL7207, it was hypothesized that monocyte populations may underpin the tumor‐growth inhibition effects of SL7207." (PMID 34633664, 2021). "Moreover, IL-1β, CCL2, PGE2, among other chemotactic factors, attract natural immunosuppressive cells, including T regulatory (Tregs), myeloid-derived suppressor cells (MDSCs), and M2 macrophages, to the tumor microenvironment." (PMID 32555170, 2020). "The inflamed tumor profile is characterized by the infiltration of immune effector cells [e.g., CD8+ T cells and type 1 T helper (TH1) cells] and proinflammatory cytokines [e.g., interleukin (IL)-12, IL-1β, and type I and type II interferons (IFNs)] in the tumor parenchyma." (PMID 32083005, 2020). "Moreover, macrophages secrete immunosuppressive IL-10 in WT mice, whereas IL-12 secreted by dendritic cells in mice lacking IL-1β expression stimulates anti-tumor immunity." (PMID 32604862, 2020).
tumor (continued). "We have confirmed that indeed moDCs show maturation features when in the presence of supernatant of tumor cells treated with the highly cytotoxic NB-PDT, including upregulation of the maturation markers CD86 and MHC II and increased secretion of IL12-p40, IL-1β, and IL-10." (PMID 32326519, 2020). "Lipids arising from adipocytes have been demonstrated to increase tumor growth and invasiveness by increasing the expression of fatty acid binding protein 4 (FABP4), a fatty acid chaperone that is involved in glucose and lipid metabolism, heme oxygenase 1 (HMOX), and IL-1β in metastatic tumor cells." (PMID 32092997, 2020). "For example, BRAF inhibitors vemurafenib and dabrafenib were shown to enable IL-1β secretion by human and murine DCs, but the authors did not explain whether this action on IL-1β was pro- or anti-tumor." (PMID 32635472, 2020). "It is possible that in non-rapid recurrence of ES-LUAD patients, higher level of IL-1β may promote the proliferation or replication of TILs within tumors to exert anti-tumor immunity." (PMID 32556504, 2020). "Contrarily, IL-1β within the tumor microenvironment has been reported to promote carcinogenesis, tumor growth, and metastasis through driving chronic non-resolved inflammation, endothelial cell activation, tumor angiogenesis, and the induction of immune-suppressive cells." (PMID 33322487, 2020). "Moreover, extracellular ATP released by tumor cells after chemotherapy can promote anti-tumor immunity via signaling through ATP-receptors P2RX7 on DCs, thereby activating the NLRP3 inflammasome, enhancing IL-1β secretion and boosting CD8+ T cell priming." (PMID 33013685, 2020). "In different tumor models, it was shown that IL-1β injection may or may not decrease tumor growth, depending on the setting of the experiment." (PMID 32635472, 2020). "Interestingly, our results revealed that priming of tumor cells with LPS increased the release of IL1-β and IL-18 without the requirement for the second stimulus (Nigericin)." (PMID 33613529, 2020). "However, since systemic IL-1β measured in the serum was not appreciably altered, it suggested a more localized periodontal signaling in the tumor bearing mice with PI." (PMID 31685946, 2020). "IL-1β is abundant in the TME, where this cytokine can promote tumor growth and presents anti-tumor activities; thus, alteration of TME from pro-invasive inflammation towards anti-tumor cell immunity against an overwhelming immunosuppressive situation is a strategy for treating cancer." (PMID 33613533, 2020). "However, the actual role of IL-1β within the inflammatory networks of the tumor environment has not been investigated to date." (PMID 32069807, 2020). "Indeed, IL-1β induces antigen-specific T cell responses by driving polarization of CD4+ T cells towards T helper type (Th) 1 and Th17 cells and enhances adaptive anti-tumor responses." (PMID 32516941, 2020). "Moreover, the increased bacterial burden seen in these mice was correlated with increased expression of cytokines such as IL-1β and IL-23 within the tumor of tumor-bearing mice not seen in GF mice." (PMID 33375062, 2020). "Differences might be because of the means used to invalidate IL-1β, that is, KO mice with no IL-1β in the host, but with tumor cells producing IL-1β, or neutralizing antibody with a decrease, but not inhibition of both host and tumor IL-1β." (PMID 32635472, 2020). "In particular, tumor cells release chemokines (such as, SDF-1, MIP-1, MCP-1, MIP-2, etc.)that trigger the activation of SRC kinase in immune cells, which in turn release other cytokines (TNF-α, IL-1β, IL-6, etc.)reciprocally activating SRC in cancer cells through a positive feedback mechanism." (PMID 32545574, 2020).
tumor (continued). "Clinical and experimental data indicate that, in the large majority of cancers, TAMs acquire an M2-like tumor-promoting phenotype characterized by high levels of immunosuppressive markers (e.g., ARG1, MMR1, IL10), as opposed to low levels of inflammatory cytokines (e.g., IL-12, IL1β, TNFα)." (PMID 32823961, 2020). "Moreover, the therapeutic response of two independent tumor models to treatment with doxorubicin diminishes upon treatment with an anti-IL-1β, but not an anti-IL-1α neutralizing antibody." (PMID 33584721, 2020). "Strikingly, the DAI score, tumor multiplicity and IKK-β mRNA abundance were significantly decreased in the CACMe group compared to the CACM group, whereas the tumor multiplicity and the COX-2 and IL-1β mRNA abundance were significantly increased in the CMCOSe group compared to the CMCOS group." (PMID 31620100, 2019). "Moreover, the use of combination therapy that includes endocrine therapy along with IL1β and PDGF-BB signaling blockers might provide more definitive data with respect to decreased tumor cell density." (PMID 31419632, 2019). "Moreover, blockade of IL-4 resulted in overexpression of pro-inflammatory cytokines (CXCL10, IL-1β, IL-15, IL-10 and IL-6) and lower expression of immunosuppressive molecules (Foxo3, IDO1 and PD-L1) as compared to cryo-thermal eosinophils + tumour-bearing DCs group." (PMID 31519961, 2019). "Besides the induction of TAM polarization in peritumoural macrophages, the tumour microenvironment can facilitate tumour cell growth by inducing an IL-1β-dependent auto-inflammatory loop involving non-cancerous cells." (PMID 31480312, 2019). "Indeed, IL-1β, TNF-α, and IFN-γ levels decreased in tumor-bearing p2x7-/- mice whereas TGF-β increased, confirming the hypothesis that P2X7 deficiency favors immune suppression." (PMID 30655604, 2019). "The ΔppGpp S. typhimurium lipopolysaccharide (LPS) promoted mononuclear/macrophage and dendritic cells to secrete IL-1β through the TLR4 signaling pathway, exerting anti-cancer effects, but tumor recurrence occurred in late treatment stages, which might be related to reduced IL-1β levels." (PMID 31754923, 2019). "However, the tumor microenvironment consists of activated TAFs that do not show sustained IL1β secretion, suggesting that TAFs require the presence of ER+BCCs to maintain IL1β secretion." (PMID 31419632, 2019). "As previously discussed, IL-1β is not restricted to the tumor microenvironment." (PMID 31174326, 2019). "However, whether, where and how IL-1β secretion and potentially the activation of the NLRP3 or other inflammasomes could occur in tumor tissues remain elusive." (PMID 30832375, 2019). "As expected, the tumor-bearing DCs co-cultured with cryo-thermal macrophages were highly matured, as demonstrated by the increased percentage of CD11c+CD86+MHC II+ DCs along with the higher relative expression of IL-6, TNF-α, CXCL10, IL-1β, IL-12p40, and IL-15 mRNA." (PMID 30833570, 2019). "Hypoxic tumor cells secrete angiogenic cytokines, such as vascular endothelial growth factor (VEGF), platelet-derived growth factor (PDGF) and basic fibroblast growth factor (bFGF) that stimulate neovascular formation and inflammatory cytokine, such as TNF-α and IL-1β." (PMID 31653130, 2019). "Similar to IL-1β, IL-6 is not restricted to the tumor microenvironment." (PMID 31174326, 2019). "We identified the CT tumor anatomic region as harboring the majority of genes significantly differentially expressed between the two neurologic deficits groups, with IL1A (interleukin 1 alpha) and IL1B (interleukin 1 beta) as putative regulators of their expression profile changes." (PMID 31231419, 2019). "This may have been a result of the tumor cells upregulating heparanase in response to stimuli from the tumor microenvironment, which could include soluble factors such as TNF-α and IL-1β, or heparanase may have originated from other cell types within the tumor microenvironment (e.g., macrophages)." (PMID 31110966, 2019).